DMD (dystrophin)
Diseases named in the same sentence as DMD in open-access papers (continued):
Sharing a sentence is not in itself a finding about the gene and the disease.
Duchenne muscular dystrophy (continued). "Duchenne muscular dystrophy (DMD) is a severe muscle-wasting disease that affects 1 in 3500 male births worldwide, which is caused by mutations in the X-linked gene encoding the cytoplasmic protein dystrophin." (PMID 32707682, 2020). "This promoter was shown to direct robust micro-dystrophin expression in a systemic gene replacement clinical trial for Duchenne muscular dystrophy." (PMID 33260623, 2020). "Further clinical studies demonstrated the efficacy of aminoglycosides G418 and gentamicin in restoring a significant amount of functional CFTR and dystrophin proteins in CF and Duchenne muscular dystrophy (DMD), respectively." (PMID 32630050, 2020). "The retention of intronic sequence in mature DMD mRNA has been reported in patients with Duchenne muscular dystrophy." (PMID 32859695, 2020). "Duchenne muscular dystrophy (DMD) is a disabling genetic disorder, due to an X-linked myopathy that prevents the production of dystrophin, a normal muscle protein." (PMID 31923192, 2020). "Duchenne muscular dystrophy (DMD, OMIM ∗310200) is a rare hereditary disease due to mutations in the dystrophin (DMD) gene, which maps to the X-chromosome (Xp21.1), and affects 1 in 5,000 newborn males." (PMID 32719714, 2020). "Transplantation of autologous, skeletal muscle-derived stem cells that have been genetically corrected to express dystrophin is a promising strategy to treat Duchenne muscular dystrophy (DMD)." (PMID 32998454, 2020). "Duchenne muscular dystrophy (DMD) is an X-linked recessive disease resulting in the loss of dystrophin, a key cytoskeletal protein in the dystrophin-glycoprotein complex." (PMID 32075145, 2020). "Among these RNA therapeutics, Eteplirsen and Golodirsen influence the splicing of dystrophin to treat Duchenne muscular dystrophy (DMD), while Nusinersen promotes a full-length splice variant of SMN2 mRNA that is effective in reducing the symptoms associated with spinal muscular atrophy (SMA)." (PMID 33352769, 2020). "Duchenne muscular dystrophy (DMD) is an X-linked, recessive disease caused by out of frame mutations in the dystrophin gene." (PMID 32227114, 2020). "Initial preclinical studies on ataluren’s potential in nonsense suppression therapy were related to Duchenne muscular dystrophy DMD, a rare genetic disorder caused by mutations in the gene for dystrophin." (PMID 31972957, 2020). "One study showed that a HAC vector carrying whole dystrophin (DMD) genomic sequence rescued dystrophin expression of Duchenne muscular dystrophy (DMD) in patient-specific iPSCs." (PMID 32922264, 2020). "Another approach for large gene sizes has been applied for Duchenne muscular dystrophy caused by the dystrophin gene (DMD) mutations (11 kb-long coding sequence where shorter synthetic dystrophin versions, known as microdystrophins, have been developed, allowing transduction by AAV vectors." (PMID 33121974, 2020). "Duchenne muscular dystrophy (DMD) is caused by mutations in the dystrophin gene, which lies on the X chromosome, where the loss of a functional dystrophin protein causes muscle wasting with an incidence of 1 in 5000 to 1/6000 boys." (PMID 32722643, 2020). "These maneuvers designed for repairing DMD alleles causing Duchenne muscular dystrophy (DMD), led to the synthesis of in-frame mRNA transcripts encoding a truncated yet potentially functional Becker-like dystrophin protein." (PMID 32295080, 2020). "As mentioned in “Duchenne Muscular Dystrophy: an overview”, neuronal nitric oxide synthase (nNOS) represents an important part of the DGC complex and dystrophin deficiency results in disturbed nNOS-NO signaling." (PMID 32691346, 2020). "Duchenne muscular dystrophy (DMD) is the most common X‐linked progressive muscle disease in humans, affecting up to 1 in 3600 live male births, with about one third of cases attributable to new spontaneous mutations in the dystrophin gene." (PMID 32869445, 2020).
Duchenne muscular dystrophy (continued). "In Duchenne muscular dystrophy (DMD), the absence of the dystrophin protein causes a variety of poorly understood secondary effects." (PMID 32019766, 2020). "The application of muscle-specific CRISPR-Cas9 dystrophin gene editing was able to ameliorate pathophysiology in a mouse model for Duchenne muscular dystrophy." (PMID 33304456, 2020). "One example is Duchenne muscular dystrophy (DMD), the most prevalent childhood-onset muscular dystrophy, where progressive muscle degeneration and weakness is caused by mutations in the DMD gene, leading to loss of dystrophin protein production." (PMID 33080928, 2020). "Duchenne muscular dystrophy (DMD) is a progressive, degenerative muscular disorder and cognitive dysfunction caused by mutations in the dystrophin gene." (PMID 33208172, 2020). "The study shows that the inhibition of Celf2a splicing factor isoform is able to partially restore dystrophin production in a subgroup of patients affected by Duchenne Muscular Dystrophy (DMD)." (PMID 32596946, 2020). "Duchenne muscular dystrophy (DMD) is a severe, progressive neuromuscular disorder caused by mutations in the DMD gene resulting in loss of functional dystrophin protein." (PMID 33551769, 2020). "Arising from the ablation of the cytoskeletal protein dystrophin, Duchenne Muscular Dystrophy (DMD) is a debilitating and fatal skeletal muscle wasting disease underpinned by metabolic insufficiency." (PMID 31980663, 2020). "Duchenne muscular dystrophy (DMD) is a severe neuromuscular disorder caused by mutations in the X-linked DMD gene, which encodes the protein dystrophin." (PMID 33059738, 2020). "The authors used AAV viral vectors to edit via CRISPR-Cas9 specific regions of the gene responsible for the Duchenne muscular dystrophy and found that the treated muscles express dystrophin in up to 70% of the myogenic area and increased force." (PMID 33304456, 2020). "Based on the mutation pattern, muscular dystrophies with DMD mutations are classified into one of the two types; Duchenne muscular dystrophy, caused by an out-of-frame DMD mutation, or Becker muscular dystrophy (BMD), caused by an in-frame DMD mutation." (PMID 33046751, 2020). "Nineteen eighty-six was a pivotal year, when the DMD gene associated with Duchenne muscular dystrophy (DMD) was discovered, followed the next year by the identification of the encoded protein dystrophin." (PMID 32727611, 2020). "For example, Duchenne muscular dystrophy (DMD), Becker muscular dystrophy (BMD), exhibiting absence or mutations in dystrophin, and tibial muscular dystrophy (TMD), exhibiting mutations in titin." (PMID 32937737, 2020). "In clinical applications, gentamicin was used in CF and DMD (Duchenne muscular dystrophy) patients with restoration of a significant amount of functional CFTR protein or dystrophin." (PMID 31972957, 2020). "This reduced expression of dystrophin ultimately gives rise to Duchenne muscular dystrophy, intermediate muscular dystrophy, or Becker muscular dystrophy (BMD)." (PMID 33050418, 2020). "Exon skipping therapy was first proposed by us as a treatment of Duchenne muscular dystrophy (DMD), a fatal progressive muscle wasting disease, in which out-of-frame DMD mRNA is transformed into in-frame to resume protein production." (PMID 33266296, 2020). "Pathology of Duchenne Muscular Dystrophy (DMD) arises from the mutation in dystrophin gene." (PMID 31998814, 2019). "Duchenne’s muscular dystrophy (DMD) paves the way forward, with 26 out of 42 studies reporting different strategies on DMD gene editing in different models of the disease." (PMID 30794581, 2019). "Modifications of this grid in the mdx mouse model of Duchenne muscular dystrophy have led to identifying dystrophin, the protein missing in both human disease and mouse model, as a microtubule guide." (PMID 31620435, 2019). "Duchenne muscular dystrophy (DMD) is a genetic disease evoked by a mutation in the dystrophin gene." (PMID 31412923, 2019).
Duchenne muscular dystrophy (continued). "AON treatment corrected the open reading frame of the dystrophin DMD mRNA and ameliorated symptoms in Duchenne muscular dystrophy patients." (PMID 30664691, 2019). "One more example is the Duchenne Muscular Dystrophy (DMD), the most common type of muscular dystrophy, has mutation in dystrophin gene affecting about one in 5,000 males at birth." (PMID 31850331, 2019). "We found that myogenic cells derived from extra eyelid tissue proliferated and differentiated myofibers in vitro, and restored DYSTROPHIN or PAX7 expression after transplantation with these cells in mice with Duchenne muscular dystrophy." (PMID 31337111, 2019). "Duchenne muscular dystrophy (DMD), a rare genetic disorder characterized by progressive muscle weakness, is caused by the absence or a decreased amount of the muscle cytoskeletal protein dystrophin." (PMID 30621068, 2019). "Duchenne Muscular Dystrophy (DMD) is one of the most severe dystrophies and is caused by the loss of functional dystrophin protein owing to genetic mutations, consequently, the sarcolemma becomes fragile and susceptible to muscle damage induced by contraction." (PMID 31626629, 2019). "Duchenne muscular dystrophy (DMD) is one of the most common and severe of the muscular dystrophies that are caused by mutations in a large gene located at Xp21, which encodes the muscle protein dystrophin." (PMID 30845639, 2019). "Duchenne muscular dystrophy (DMD) is a fatal muscular disorder caused by nonsense mutations, large deletions or duplications in the dystrophin gene." (PMID 30760802, 2019). "Duchenne muscular dystrophy (DMD) is a recessive, X-linked neuromuscular disorder caused by mutations in the dystrophin gene, and is characterised by progressive degeneration of skeletal and cardiac muscles." (PMID 31479456, 2019). "Muscle dystrophy is a genetic disease; Duchenne muscular dystrophy (DMD), caused by the mutation of the dystrophin gene on the X chromosome, is the most common and severe type of muscle dystrophy." (PMID 31461973, 2019). "Duchenne muscular dystrophy (DMD) is the most common muscular dystrophy among children affecting mostly males (1:5000) and is caused by mutations in the dystrophin gene." (PMID 33072985, 2019). "Similarly, somatic correction of Duchenne muscular dystrophy (DMD) caused by a mutation in the gene encoding dystrophin has been reported, showing a 70% increase in functional dystrophin and apparent improvement in the mouse model." (PMID 29515088, 2018). "Duchenne muscular dystrophy (DMD) is a monogenic, X-linked, progressive neuromuscular disease caused by mutations in the gene encoding dystrophin, a critical structural protein of skeletal, cardiac, and smooth muscle." (PMID 30368252, 2018). "Duchenne Muscular Dystrophy (DMD) is a progressive and lethal disease, caused by X-linked mutations of the dystrophin encoding gene." (PMID 29546607, 2018). "Duchenne muscular dystrophy (DMD) is a lethal disorder caused by mutations in the DMD gene." (PMID 29301272, 2018). "Over the past decade different stem cell (SC) based approaches were tested to treat Duchenne Muscular Dystrophy (DMD), a lethal X-linked disorder caused by mutations in dystrophin gene." (PMID 29305755, 2018). "Duchenne muscular dystrophy (DMD) is a lethal X-chromosome-linked recessive disorder, affecting 1 in 3500–5000 male births, caused by various mutations in a gene encoding a membrane-associated protein—dystrophin." (PMID 30025544, 2018). "Duchenne muscular dystrophy (DMD) is a severe type of muscular dystrophy, in which mutations of the dystrophin gene lead to progressive muscle wasting and degeneration." (PMID 30510631, 2018). "A paradigm is Duchenne muscular dystrophy (DMD), an incurable disorder caused by mutations in the largest human gene: dystrophin." (PMID 29242210, 2018).
Duchenne muscular dystrophy (continued). "Duchenne muscular dystrophy (DMD), caused by mutations in the gene encoding for the cytoskeletal protein dystrophin, is linked with severe cardiac complications including cardiomyopathy development and cardiac arrhythmias." (PMID 29333726, 2018). "A long-standing mystery in the Duchenne muscular dystrophy (DMD) field is how the spectrin-like repeats of dystrophin, and the adaptor protein α-syntrophin cooperate to localize neuronal nitric oxide synthase mu (nNOSμ) to the sarcolemma." (PMID 30349485, 2018). "Duchenne muscular dystrophy (DMD, MIM 310200) is a severe form of muscular dystrophy caused by mutations in the dystrophin gene (DMD) that leads to a lack of dystrophin protein production, and results in muscle degeneration and premature death of the patients." (PMID 29579078, 2018). "About 15% of Duchenne muscular dystrophy (DMD) cases are caused by point mutations leading to premature stop codons and disrupted synthesis of the dystrophin protein." (PMID 30406066, 2018). "Duchenne muscular dystrophy (DMD), induced by mutations in the gene encoding for the cytoplasmic protein dystrophin, is a severe inherited disease characterized by progressive muscle weakness and degeneration." (PMID 29333726, 2018). "Duchenne muscular dystrophy (DMD) is the most common muscular dystrophy among children affecting mostly males (1:5000) and caused by mutations in the dystrophin gene." (PMID 33072949, 2018). "Duchenne muscular dystrophy is a highly progressive muscle wasting disease with a complex pathophysiology that is based on primary abnormalities in the dystrophin gene." (PMID 29679381, 2018). "To evaluate the involvement of protein quality control in Duchenne muscular dystrophy, we first analyzed the protein aggregation status of control (W1 and W2) and DMD (D1–D4) immortalized myoblast cell lines." (PMID 29316663, 2018). "The clinical challenge presented by FOP is notably distinct from other disabling pathologies such as Duchenne Muscular Dystrophy (DMD), which is associated with loss of function mutations in the dystrophin gene DMD." (PMID 28918311, 2018). "A representative example of this approach is exon skipping for Duchenne muscular dystrophy (DMD), where the muscular protein dystrophin is prematurely truncated by mutations that disrupt the open reading frame, thus leading to a non-functional protein." (PMID 28045043, 2017). "Duchenne muscular dystrophy (DMD) (OMIM #310200) is an X-linked, recessive disorder involving a mutation in the dystrophin gene DMD (OMIM #300377) on Xp21." (PMID 28895939, 2017). "Exon skipping mediated by tricyclo-DNA (tc-DNA) antisense oligonucleotides has been shown to induce significant levels of dystrophin restoration in mdx, a mouse model of Duchenne muscular dystrophy." (PMID 29246319, 2017). "Duchenne muscular dystrophy (DMD) is a devastating, progressive neuromuscular disease caused by mutations in the gene encoding the cytoskeletal protein dystrophin." (PMID 29326947, 2017). "Duchenne muscular dystrophy (DMD), caused by mutations in the gene encoding for the cytoskeletal protein dystrophin, is a severe illness characterized by progressive muscle weakness and degeneration." (PMID 27560040, 2017). "These reprogrammed cells formed Dystrophin-positive mature muscle fibers when transplanted into a mouse model of Duchenne muscular dystrophy." (PMID 28808339, 2017). "One example of this scenario is provided by the severe Duchenne Muscular Dystrophy (DMD), caused by mutations in the dystrophin gene located on the X chromosome, where it spans 2.2 megabases of DNA." (PMID 28616376, 2017). "Among them, antisense oligonucleotide (AO)-mediated exon-skipping has been demonstrated as a promising therapy to treat Duchenne muscular dystrophy (DMD) by facilitating ‘skipping’ of specific dystrophin gene exon(s) to restore the reading frame of the mutated transcripts." (PMID 28633548, 2017).
Duchenne muscular dystrophy (continued). "CD29+, CD44+, CD59+, and CD90+ cells from menstrual blood are capable of differentiating into myoblasts/myocytes and conferring human dystrophin expression in the murine model for Duchenne muscular dystrophy." (PMID 28706537, 2017). "Inflammation plays a considerable role in the progression of Duchenne Muscular Dystrophy (DMD), a severe muscle disease caused by a mutation in the dystrophin gene." (PMID 28089792, 2017). "Duchenne Muscular Dystrophy (DMD) is an X-linked recessive myodegenerative disease that is manifest in males from early childhood onwards owing to the absence or vast reduction of dystrophin." (PMID 27660108, 2016). "The greater susceptibility to contraction-induced skeletal muscle injury (fragility) is an important dystrophic feature and tool for testing preclinic dystrophin-based therapies for Duchenne muscular dystrophy." (PMID 27441081, 2016). "Second, insertion of larger DNA fragments can be achieved by plasmid donors, and has been applied for targeted correction of exon deletions in the Dystrophin gene in Duchenne muscular dystrophy patient cells." (PMID 27910942, 2016). "The most severe neuromuscular disease is the Duchenne Muscular Dystrophy (DMD), a rare X-linked genetic disease caused by mutations in the dystrophin gene." (PMID 26839565, 2016). "Autologous stem cells that have been genetically modified to express dystrophin are a possible means of treating Duchenne Muscular Dystrophy (DMD)." (PMID 26813695, 2016). "Duchenne muscular dystrophy (DMD) is a recessive genetic disorder, caused by thealteration of the gene that encodes dystrophin protein, which is essential formaintaining the muscle cell membrane." (PMID 27333479, 2016). "Finally, in Duchenne muscular dystrophy (DMD), primary deficiency of dystrophin leads to several secondary pathological changes including ECM breakdown, inflammation, and fibrosis, all of which require MMP activity." (PMID 28042204, 2016). "Another recessive X-linked disease the Duchenne muscular dystrophy (DMD), is primarily caused by a frame-shift mutation in dystrophin protein which is essential for proper functioning of muscles, and is very much suitable for genome editing inspite of its very large size of 79 exons." (PMID 27250031, 2016). "Duchenne muscular dystrophy (DMD) is the most common and severe form of muscular dystrophy and is caused by mutations in the gene that encodes the cytoskeletal protein dystrophin." (PMID 27073590, 2016). "Duchenne muscular dystrophy (DMD) and its milder form, Becker muscular dystrophy (BMD) are X-linked recessive muscular dystrophy caused by mutations in the dystrophin gene (DMD) on chromosome Xp21.2." (PMID 25612904, 2015). "In contrast, the majority of patients in a Phase 2a clinical trial for Duchenne muscular dystrophy showed a PTC124 mediated increase in dystrophin levels." (PMID 25292197, 2015). "We have recently shown that indel mutations in more than 87 % of the monkey dystrophin gene is sufficient to lead to the loss of expression of dystrophin and consequently results in muscle degeneration as seen in Duchenne muscular dystrophy (DMD)." (PMID 26238861, 2015). "An ethylnitrosourea-induced genetic dystrophin mutant sapje has been shown to recapitulate a spectrum of phenotype of human Duchenne muscular dystrophy (DMD)." (PMID 26186000, 2015). "RNA-based therapeutics and splice-switching approaches have been explored over the past decade for treating various diseases, including Duchenne muscular dystrophy (DMD), a severe muscle disorder caused by mutations in the large modular protein dystrophin." (PMID 25759365, 2015). "The most common and severe form is Duchenne muscular dystrophy (DMD), which is caused by mutations in the dystrophin gene." (PMID 26536238, 2015). "A common and severe form of muscular dystrophy is Duchenne muscular dystrophy (DMD), caused by mutations in the dystrophin gene." (PMID 25949786, 2015).